EIF2AK4 (eukaryotic translation initiation factor 2 alpha kinase 4)
Diseases named in the same sentence as EIF2AK4 in open-access papers (continued):
Sharing a sentence is not in itself a finding about the gene and the disease.
triple-negative breast carcinoma (3 papers, 2015 to 2021). An invasive breast carcinoma which is negative for expression of estrogen receptor (ER), progesterone receptor (PR), and human epidermal growth factor receptor 2 (HER2). "A germline mutation in EIF2AK4 (rs35602605) was present in 46% of the triple negative breast cancer (TNBC) cases compared to 27% of the ER-positive/HER2-negative (ER+) cases (P = 0.009), confirming the results from our cohort." (PMID 26420498, 2015).
cutaneous melanoma (1 paper, 2022). A primary melanoma arising from atypical melanocytes in the skin. "All the significant correlations showed an inverse association between CpG methylation and RNA expression levels of each gene, with TAPBP showing hypomethylation while EIF2AK4 showing hypermethylation in UV-mutant relative to non UV-mutant cutaneous melanoma patients." (PMID 35840550, 2022).
idiopathic pulmonary arterial hypertension (1 paper, 2021). A sporadic form of pulmonary arterial hypertension (PAH) characterized by elevated pulmonary arterial resistance leading to right heart failure. "The diagnosis of idiopathic pulmonary arterial hypertension was corrected by eukaryotic translation initiation factor 2 alpha kinase 4 (EIF2AK4) mutation screening." (PMID 34731104, 2021).
liver cirrhosis (1 paper, 2016). "At the same time, the EIF2AK4 mutation was most likely also present in the grandfather (I:1), who had died aged 49 years due to liver cirrhosis." (PMID 27809840, 2016).
small cell lung carcinoma (1 paper, 2025). Small cell lung cancer (SCLC) is a highly aggressive malignant neoplasm, accounting for 10-15% of lung cancer cases, characterized byrapid growth, and early metastasis. "More recently, in small-cell lung cancer models, a CRISPR-Cas9 screen implicated the kinase GCN2 (encoded by EIF2AK4) as being rapidly activated by AZD1775 via an off-target mechanism; GCN2 triggers the integrated stress response (ISR) and contributes to the cytotoxicity of the drug." (PMID 41343527, 2025).
tongue cancer (1 paper, 2022). A malignant neoplasm affecting the tongue. "Among them, AC099850.3 is the most co-expressed lncRNA, which is related to six differently expressed mRNAs, namely (CAV1, NRAS, ACSL3, AURKA, EIF2AK4 and RRM2), and its high expression level is closely related to the reduction in the survival rate of patients with tongue cancer." (PMID 35299954, 2022).
veno-occlusive disease (1 paper, 2016). "In the same manner, mutations in the eukaryotic translation initiation factor 2α kinase 4 (EIF2AK4) gene have recently been identified as disease causing in families with recessively inherited veno-occlusive disease and pulmonary capillary haemangiomatosis." (PMID 27809840, 2016). "Mutations in the eukaryotic translation initiation factor 2α kinase 4 (EIF2AK4) gene have recently been identified in recessively inherited veno-occlusive disease." (PMID 27809840, 2016).
tumor (95 papers, 2013 to 2026). "EIF2AK4 drives a shift in the phenotype of tumor-associated macrophages and myeloid-derived suppressor cells that promotes antitumor immunity." (PMID 35954244, 2022). "The EIF2AK4 pathway, involved in the cellular response to amino acid deprivation and metabolic stress, has been linked to tumor adaptation under nutrient-limited conditions, which is particularly relevant for PDAC’s hypoxic and nutrient-deprived microenvironment." (PMID 40559993, 2025). "We next investigated the other set of terms shared by a subpopulation of cells in all active-MM tumours (Similarity Program A), which revealed an interesting pattern of biological pathways including “Translation” and “Response of EIF2AK4 to amino acid deficiency”." (PMID 34732728, 2021). "EIF2AK4 (or GCN2) has been found to affect the survival of tumor patients by suppressing cancer immunology." (PMID 37138885, 2023). "Normally, as tumor growth progresses, access to nutrients such as amino acids decreases, which activates EIF2AK4 to induce downstream effects of increased tumor cell survival and treatment resistance." (PMID 36497269, 2022). "Interestingly, amino acid deprivation-induced VEGF expression is evident in human tumors and tumor cell lines, suggesting that the EIF2AK4/ATF4 axis stimulates tumor angiogenesis." (PMID 36293401, 2022). "Furthermore, DNA methylation analysis revealed that specific loci in PDX1, EIF2AK4, ASNS, DNAJB2, and FBOX6 were hypomethylated in tumor samples." (PMID 35884393, 2022). "However, EIF2AK4 and FBOX6 showed loss of CNV, but their expression was increased, whereas other genes with increased or decreased CNV or differentially methylated DNA loci showed no expression disparities between normal and tumor tissues." (PMID 35884393, 2022). "Other genes, such as ASNS, EIF2AK4, ERMP1, and HYOU1, showed an increasing trend in tumor tissue, but this was not statistically significant." (PMID 35884393, 2022).
cancer (79 papers, 2010 to 2026). A tumor composed of atypical neoplastic, often pleomorphic cells that invade other tissues. "Several additional highly connected pathways were identified, including the RAF/MAP kinase cascade, mitotic metaphase and anaphase, and response of EIF2AK4 (GCN2) to amino acid deficiency, all of which are relevant to cancer progression and therapy resistance." (PMID 40559993, 2025). "ATF4 is selectively translated in cancer cells in response to amino acid starvation during the integrated stress response (ISR) via the action of the protein kinase GCN2 (encoded by the Eif2ak4 gene) that senses low cellular amino acid levels." (PMID 37998373, 2023). "Reciprocal regulation between EIF2AK3 and EIF2AK4 through the JNK–FOXO3 axis modulates cancer drug resistance and clonal survival." (PMID 35954244, 2022). "When exposed to paclitaxel, cancer cells activated the EIF2AK3/EIF2AK4‐pEIF2S1‐ATF4 axis and maintained redox homoeostasis by inducing expression of the major antioxidant enzymes HMOX1, SHMT2 and SLC7A11." (PMID 31211507, 2019). "•GCN2 (eIF2AK4) cooperates with PERK to modulate cancer drug response." (PMID 32615282, 2020). "Previous studies in Drosophila have shown that GCN2 (eIF2AK4) and PERK (eIF2AK3) can cooperate to modulate FOXO activity in response to ER stress, suggesting the PERK-related GCN2 can potentially compensate for the inactivation of PERK function in cancer cells." (PMID 32615282, 2020). "Finally, lncRNAs such as lnc-EIF2AK4-1:1, -1:4, and -1:5, as well as lnc-SERF1B-1:4 were not correlated with many of the immune-associated or cancer-associated pathways." (PMID 31810243, 2019).
infection (37 papers, 2012 to 2026). The state of being infected such as from the introduction of a foreign agent such as serum, vaccine, antigenic substance or organism. "The K12 MG1655 strain was cleared since day 1 post-infection in both Tg/eif2ak4+/+ and Tg/eif2ak4−/− mice." (PMID 30120269, 2018). "In contrast, at day 14 and 21 post-infection, patterns of clustering between eif2ak4−/− + LF82, eif2ak4+/+ + LF82, eif2ak4+/+ + PBS and eif2ak4−/− + PBS groups were observed." (PMID 30120269, 2018). "EIF2AK4 is a stress sensor gene and can be activated by pathogen infection." (PMID 35812738, 2022). "In addition, we determined AIEC LF82 colonization by quantifying pMT gene expression by qPCR at day 14 and 21 post-infection in both Tg/eif2ak4−/− and Tg/eif2ak4+/+ groups." (PMID 30120269, 2018). "Interestingly, qPCR data showed pMT gene amplification at day 14 and 21 post-infection in both eif2ak4+/+ and eif2ak4−/− groups, and the pMT gene expression level was increased in eif2ak4−/− mice compared to eif2ak4+/+ mice." (PMID 30120269, 2018). "In addition, LF82-specific pMT gene expression level in eif2ak4−/− mice was increased at day 21 post-infection compared to that at day 14 post-infection." (PMID 30120269, 2018). "Next, we analyzed the fecal microbiota composition in these mouse groups at the same time post-infection to investigate whether an altered microbiota composition could occur before or after the increase in lcn-2 level in LF82-infected eif2ak4−/− mice." (PMID 30120269, 2018). "LF82-infected eif2ak4−/− mice exhibited altered fecal microbiota composition at day 14 and 21 post-infection and increased fecal lipocalin-2 level at day 21 post-infection compared to other groups, indicating that intestinal inflammation developed after microbiota modification." (PMID 30120269, 2018). "In both eif2ak4+/+ and eif2ak4−/− mice, the colonization of AIEC LF82 bacteria was higher and lasted longer compared to that of the non-pathogenic K12 MG1655 bacteria as the LF82 strain was detectable up to day 4 post-infection, whereas the K12 MG1655 strain was cleared since day 1 post-infection." (PMID 30120269, 2018). "In contrast, after 14 and 21 days of infection, a clear pattern of clustering in eif2ak4−/− + LF82 group compared to the other groups (eif2ak4+/+ + LF82, eif2ak4+/+ + PBS and eif2ak4−/− + PBS) was observed." (PMID 30120269, 2018). "2D plotting of PCoA-1 versus PCoA-2 showed a clear difference in the microbiota composition between eif2ak4−/− + PBS and eif2ak4−/− + LF82 groups at day 14 and 21 post-infection." (PMID 30120269, 2018). "Taxonomic analysis at the genus level showed that most of the differences observed in PCoA were explained by an increase in Turicibacter and Clostridium in eif2ak4−/− + LF82 group compared to the other groups at days 14 and 21 post-infection." (PMID 30120269, 2018). "Importantly, the increased lcn-2 level in LF82-infected eif2ak4−/− mice lasted for at least twenty days, suggesting that a chronic inflammation is set up in eif2ak4−/− mice after AIEC infection." (PMID 30120269, 2018). "Interestingly, in Tg/eif2ak4+/+ mice, in contrast to eif2ak4+/+ mice, the microbiota of uninfected and LF82-infected groups diverged at day 14 and 21 post-infection." (PMID 30120269, 2018). "Infection of both Tg/eif2ak4+/+ and Tg/eif2ak4−/− with the K12 MG1655 strain did not induce any significant change in fecal lcn-2 level up to 40 days post-infection." (PMID 30120269, 2018). "For that, we generated Tg/eif2ak4+/+ and Tg/eif2ak4−/− mice and infected them with the AIEC LF82 strain or the K12 MG1655 strain using the same infection protocol as applied for eif2ak4+/+ and eif2ak4−/− mice, in which antibiotics were not used." (PMID 30120269, 2018). "However, in eif2ak4+/+ mice, this level was not increased at day 21 compared to day 14 post-infection." (PMID 30120269, 2018).
infection (continued). "However, in Tg/eif2ak4−/− mice, a significant increase in fecal lcn-2 level upon AIEC LF82 infection was observed at day 21 post-infection, and this lasted up to day 40 post-infection." (PMID 30120269, 2018). "At day 1 and 4 post-infection, we did not observe any pattern of clustering between uninfected (+PBS) or LF82-infected Tg/eif2ak4+/+ and Tg/eif2ak4−/− groups." (PMID 30120269, 2018).
connective tissue disease (1 paper, 2022). "One patient diagnosed with connective tissue disease APAH also carried two most likely bi-allelic pathogenic variants in the EIF2AK4 gene." (PMID 35346192, 2022). "Interestingly, while connective tissue disease can be a risk factor for PVOD development, characteristic bi-allelic variants in the EIF2AK4 gene addition in a connective tissue disease APAH patient have only been described in two other patients before." (PMID 35346192, 2022).
inflammation (1 paper, 2018). Aberrant reaction of the microcirculation characterized by movement of fluid and leukocytes from the blood into extravascular tissues. "Together, these data suggest that AIEC colonization in the genetically predisposed host with Eif2ak4 gene deficiency induces a change in the gut microbiota composition, which is associated with the development of chronic intestinal inflammation." (PMID 30120269, 2018). "As gut microbiota has been implicated in the etiopathogenesis of CD, we aimed at investigating whether it is associated with the AIEC-induced intestinal inflammation in genetically predisposed mouse models with Eif2ak4 gene deficiency." (PMID 30120269, 2018).
EIF2AK4 also shares sentences with these, for which no sentence is quoted: melanoma (22 papers); colon carcinoma (9); glioblastoma (8); Alzheimer disease (7); colitis (7); neurodegenerative disease (7); Obesity (6); prostate carcinoma (6); colorectal cancer (5); HIV-1 infection (5); Insulin resistance (5); Autoimmunity (4); gastric cancer (4); iron deficiency (4); myeloma (4); pancreatic cancer (4); bacterial infection (3); fibrosarcoma (3); head and neck squamous cell carcinoma (3); lung disease (3); lupus (3); memory impairment (3); acute lymphoblastic leukemia (2); bladder cancer (2); colorectal adenocarcinoma (2); Glucose intolerance (2); hematologic malignancies (2); hereditary pulmonary arterial hypertension (2); Hyperglycemia (2); influenza infection (2).
A further 84 diseases each share a sentence with EIF2AK4 in 2 papers or fewer.